TRIM37 (tripartite motif containing 37)
Diseases named in the same sentence as TRIM37 in open-access papers (continued):
Sharing a sentence is not in itself a finding about the gene and the disease.
cancer (continued). "Finding a way to keep equilibrium in the cellular expression of TRIM37 could lead to potential therapeutic treatments and future drug discoveries for developmental anomalies and cancer." (PMID 30586926, 2018). "Among non-MULIBREY patients affected by cancer, a wide variety of cancers are associated with an overexpression of TRIM37." (PMID 30586926, 2018). "Although TRIM37 mutations lead to an increased risk of tumors, this is questionable when considering cancer among non-MULIBREY patients." (PMID 30586926, 2018). "Moreover, in vitro cell experiments further demonstrated that the downregulation of TRIM37 could hamper the malignant behaviors of CC cells, indicating its crucial role in promoting cancer progression." (PMID 40158112, 2025). "Proliferation in the absence of centrioles may further be facilitated by the low-level expression of Trim37 in mature vs. progenitor B cells, as this E3 ligase was reported to antagonize acentriolar cell division increasing cancer cell vulnerability to centrinone treatment." (PMID 39406735, 2024). "This review encapsulates the latest advancements in our understanding of centriole duplication and acentrosomal cell division in the context of TRIM37 amplification, positioning PLK4 as a compelling target for innovative cancer therapeutics." (PMID 40257113, 2025). "This suggests that CTNNA1 plays a role in the anti-cancer effect of LSD1 in luminal breast cancer, while TRIM37 inhibits this anti-cancer effect." (PMID 36741258, 2023). "TRIM37 has been reported to interact with TRAF2 and TRAF6 to promote cancer cell proliferation and chemoresistance." (PMID 35163097, 2022). "Taken together, our findings uncover that TRIM37 serves as promising biomarker for RCC progression and proposes a potential therapeutic target for cancer intervention." (PMID 34130705, 2021). "Several studies proposed that excessive TRIM37 activity destabilizes PCM proteins, thereby compromising mitotic fidelity, which could contribute to cancer progression." (PMID 41446055, 2025). "To explore TRIM37-driven functional pathways in BW, we performed Gene Set Enrichment Analysis (GSEA) for upregulated genes, which identified the cancer stem cell (CSC) and epithelial to mesenchymal transitional (EMT) among the enriched gene sets (Figs. EV2B and 2D)." (PMID 39614126, 2025). "Cancer cells overexpressing TRIM37 are hypersensitive to the absence of centrioles upon treatment with the PLK4 inhibitor Centrinone, because excess TRIM37 interferes with acentriolar spindle assembly, inducing mitotic failure." (PMID 33491649, 2021). "Additionally, TRIM37 enhances the invasion and metastasis of cancer cells, such as those in colorectal, hepatocellular, non-small-cell lung cancer, pancreatic and gastric cancers." (PMID 40158112, 2025). "A recent paper identified the ubiquitin ligase TRIM37 as responsible for cancer-specific vulnerability to PLK4 inhibition, and identification of vulnerability hot spots could help PLK4 targeting in cancers." (PMID 35053604, 2022). "In several non-MULIBREY cancers, TRIM37 has been found to be overexpressed." (PMID 30586926, 2018). "The ability of TRIM37 to prevent the formation of ectopic PLK4-containing aggregates is particularly important in the context of cells lacking functional centrosomes, suggesting for example that TRIM37 could trigger selective mitotic failure in cancer types sensitive to PLK4 inhibition." (PMID 35136173, 2022).
tumor (32 papers, 2016 to 2026). "The missense mutation found in our tumor samples should be investigated for its effects on TRIM37 expression." (PMID 39086683, 2023). "Kaplan-Meier survival estimates showed that TRIM37 immunoreactivity in tumor cells was significantly associated with overall survival according to the extent of each intensity score." (PMID 33391428, 2021). "TRIM37 expression was upregulated in hepatic cancer samples and was associated with advanced stage and tumor volume." (PMID 30586926, 2018). "The decrease in TRIM37 results in loss of ubiquitinated H2A and therefore a decrease in tumor growth, while overexpression of TRIM37 induces tumorigenesis." (PMID 30586926, 2018). "Given that TRIM37 is associated with genomic instability, tumor progression, and poor prognosis, we hypothesized that TRIM37 levels in breast tissue could likely inform the clinical outcome." (PMID 39614126, 2025). "Further study revealed the underlying mechanism: TRIM37 could mono-ubiquitinate histone H2A, leading to the silencing of tumor suppressor genes, and facilitating the transformation from normal cells to tumor cells." (PMID 36261847, 2022). "High TRIM37 score was associated with advanced tumor grade and poorer survival." (PMID 34130705, 2021). "In a previous study, we showed that TRIM37 was frequently upregulated in PC and that its overexpression was positively associated with tumor growth and worse patient prognosis, leading us to hypothesize that elevated TRIM37 expression may play an important role in PC development and progression." (PMID 33194618, 2020). "Moreover, in keeping with the role of PTEN as a tumor suppressor, we found that high TRIM37 and low PTEN expression levels were associated with poorer survival in patients with PC, confirming the implications suggested by our in vitro mechanistic analyses and mouse xenograft study." (PMID 33194618, 2020). "Using structural biology‐guided approaches, Vallée and colleagues systematically validated the synthetic lethal effect of the PLK4 inhibitor RP‐1664 in TRIM37‐amplified tumours." (PMID 41537447, 2026). "In parallel, RP‐1664, a novel PLK4 inhibitor, disrupts centriole biogenesis and is effective in TRIM37‐amplified tumours." (PMID 41537447, 2026). "Then, RT-qPCR assay was used to determine TRIM37 expression levels in 34 pairs of CC tissues, which showed a higher level in the tumor tissue than in normal tissues." (PMID 40158112, 2025). "Together, these results indicate that TRIM37 upregulation in the early stages of the disease gives the tumor a “head-start” to progress and metastasize by triggering cellular reprogramming." (PMID 39614126, 2025). "Injected mice were fed on either a control or doxycycline-containing diet to allow for the continuous expression of TRIM37, and tumor growth was monitored." (PMID 39614126, 2025). "TRIM37 represses gene transcription by mono-ubiquitinating histone H2A at Lys119 (H2Aub) at various genomic loci, including tumor suppressors and pro-apoptotic genes." (PMID 39614126, 2025). "Results showed that TRIM37 overexpression markedly inhibited tumor growth, which was abolished by KIFC1 overexpression." (PMID 39349439, 2024). "Consistent data regarding tumor volume and weight further supported the notion that decreased TRIM37 expression curbs RCC cell growth." (PMID 39349442, 2024). "Our data showed that TRIM37 overexpression inhibited inflammatory injury and tumor metastasis in lung tissues, which was reversed by KIFC1 overexpression." (PMID 39349439, 2024). "The results revealed a substantial deceleration in the rate of RCC cell growth upon TRIM37 silencing, accompanied by a more pronounced anti-tumor effect of sunitinib compared to control cells." (PMID 39349442, 2024). "There has been research suggesting that there are several signaling pathways through which TRIM37 promotes tumor progression, including the Wnt/β-catenin pathway." (PMID 37379772, 2023).
tumor (continued). "The expression of TRIM37 was significantly higher in GBC tissues compared with peritumoral tissues, and its high expression was significantly associated with poor tumor differentiation, along with advanced TNM stage and a shorter OS of GBC patients." (PMID 37379772, 2023). "After investigating the immune cell population in tumor milieu, we observed that tumors with TRIM37 knockdown had significantly lower numbers of CD11b+F4/80+MHCIIlow macrophages." (PMID 35163097, 2022). "A recent study revealed that TRIM37 is an oncoprotein that facilitates the silencing of tumor suppressors by functioning as a histone H2A ubiquitin ligase." (PMID 35163097, 2022). "TRIM37 knockdown significantly inhibited tumor growth, as the bioluminescence signal in the TRIM37 knockdown group was dramatically reduced compared to that in the control groups." (PMID 35163097, 2022). "We examined the prognostic and clinicpathological significance of TRIM37 expression in primary tumor samples of GC, based on the immunohistochemical staining pattern of this protein." (PMID 33391428, 2021). "Concordant with in vitro both 2D and 3D findings, overexpressing TRIM37 of 786-O cells showed increased tumor growth rates." (PMID 34130705, 2021). "In 47 of RCC samples from NMU_RCC cohort 1, TRIM37 mRNA level was statistically elevated in tumor tissues than normal tissues and in Grade 3–4 (P < 0.0001) tumors, but not in Stage T3-T4 tumors (P = 0.0788)." (PMID 34130705, 2021). "TRIM37 is a novel discovered E3 ubiquitin ligase and acts as a oncoprotein in multiple human neoplasms, however its biological role in RCC still remains elusive." (PMID 34130705, 2021). "Our findings raise the possibility that H2A ubiquitination can involves into RCC tumor progression mediated by TRIM37." (PMID 34130705, 2021). "We also investigated the molecular mechanisms affecting the malignant potential of tumor cells resulting from the overexpression of TRIM37." (PMID 33391428, 2021). "Through mechanistically studies, we constructed a novel regulating axis of TRIM37/ub-H2A/TGF-β1/Smad2/3 signaling in regulating RCC tumor metastases and progression." (PMID 34130705, 2021). "Compared to control group, tumor xenograft generated from TRIM37 overexpression cells displayed significantly enhancive Ki67 and PCNA expression, upregulation of ub-H2A and TGF-β1 levels were also observed." (PMID 34130705, 2021). "TRIM37 overexpression in MCF7 cells led to the silencing of several tumor suppressor genes through H2A monoubiquitination, an epigenetic marker of transcriptional repression." (PMID 34208621, 2021). "ASB16-AS1 activates NF-κB pathway via inducing TRIM37 phosphorylation to facilitate tumor growth, stemness, and cisplatin resistance in GC." (PMID 34805143, 2021). "Our study illustrated that abnormal TRIM37 was correlated with adverse histological tumor grade, overall and relapse-free survival of RCC patients." (PMID 34130705, 2021). "Subsequent biological exploration confirmed TRIM37 was required for maintaining tumor cells migration and invasion phenotype in vitro and in vivo." (PMID 34130705, 2021). "Mechanistically, ASB16-AS1 activates the NF-κB pathway via inducing TRIM37 phosphorylation to facilitate tumor growth, stemness, and cisplatin (CDDP) resistance in GC." (PMID 34805143, 2021). "Next, to determine the metastatic capability of RCC cells of 3D models, we conducted tumor spheroid invasion assay and showed that elevating TRIM37 significantly accelerated tumor spheroid invasive ability in RCC cells." (PMID 34130705, 2021). "We found that TRIM37 overexpression significantly increased tumor growth in 5-FU-treated mice, whereas downregulation of TRIM37 significantly inhibited tumor growth." (PMID 33194618, 2020).
tumor (continued). "Finally, the ectopic expression of TRIM37 enabled xenograft tumor formation in mice, with the K51t-TRIM37 tumors showing accelerated growth relative to control cells." (PMID 39614126, 2025). "TRIM37 overexpression counteracted ATF6 knockdown’s impact on tumor growth in vivo." (PMID 40158112, 2025). "TRIM37 overexpression counteracts ATF6 knockdown’s impact on tumor growth in vivo." (PMID 40158112, 2025). "Interestingly, a subset of tumor-bearing animals, when deprived of a doxycycline diet, showed a marked reduction in the tumor growth, indicating the role of TRIM37 in early stages of tumorigenesis." (PMID 39614126, 2025). "Our results revealed elevated TRIM37 expression in both RCC patient tumor tissues and RCC cells." (PMID 39349442, 2024). "Moreover, Western blot analysis revealed that TRIM37 protein expression was higher in tumor samples." (PMID 39349442, 2024). "Additionally, our investigation revealed upregulation of TRIM37 in RCC tumor samples compared to corresponding adjacent tissues." (PMID 39349442, 2024). "In addition, TUNEL staining further indicated that TRIM37 resulted in increased apoptosis to suppress tumor growth, which was inhibited by KIFC1 overexpression." (PMID 39349439, 2024). "The initial EMC may have been driven by SNPs in MYO18B, TRIM37, and IL7R; or loss of tumor suppressor genes on chromosome 10q." (PMID 39086683, 2023). "TRIM37 knockdown significantly inhibited xenograft tumor formation and growth." (PMID 37379772, 2023). "Additionally, IHC staining indicated that TRIM37 knockdown xenograft tumor tissue had a decreased expression of cell proliferation marker Ki-67." (PMID 37379772, 2023). "A recent study revealed that the TRIM29 and TRIM37 genes were involved in the cell response to radiation and could function as predictive biomarkers for radiation sensitivity in normal and tumor cell lines." (PMID 36261847, 2022). "In the scores of intensities, the TRIM37 high-expression group, with a score ≥ 2 for tumor cells showing immunopositivity, showed significantly poorer overall survival (P = 0.0057, log-rank test) and relapse-free survival (P = 0.0288, log-rank test) compared with the low-expression group." (PMID 33391428, 2021). "Taken together, we could preliminarily clarify that the promoting function of TRIM37 in RCC tumor progression relies on TGF-β1 signaling." (PMID 34130705, 2021). "A Cox proportional hazards regression analysis identified TRIM37 immunoreactivity in tumor cells as an independent factor that predicted a worse overall survival rate (hazard ratio 3.41; 95% confidence interval: 1.22-11.3), along with advanced pathological stage." (PMID 33391428, 2021). "In addition, we identify a significant correlation between the prognosis of PC patients and tumor expression levels of TRIM37 and PTEN, confirming the clinical relevance and potential therapeutic utility of our results." (PMID 33194618, 2020). "FBXL19-AS1 might act as the inducible endogenous RNA of hsa-miR-20b-5p to influence the expression of BTG3, KIF23, RBBP7, and TRIM37 and regulate tumorigenesis, Wnt/β-catenin pathway, tumor metastasis as well as apoptosis." (PMID 33344260, 2020). "Recent advances have expanded understanding of TRIM37 function, linking it to mTORC1 TFEB signalling autophagy, centrosome integrity, extracellular matrix regulation, and immune cell function, providing mechanistic insights into tumour predisposition, skeletal pathology, and immune dysregulation." (PMID 42123650, 2026).
tumor (continued). "Finally, the functions of TRIM37 in vivo were investigated by establishing a xenograft tumor model." (PMID 40158112, 2025). "Additionally, Nude mice with TRIM37 knockdown show decreased tumor growth in vivo." (PMID 37379772, 2023). "In addition, TRIM37 could increase the proportion of pro-tumor macrophages to enhance tumor progression." (PMID 35163097, 2022). "In addition, the tumor weight was decreased considerably in the TRIM37 knockdown group." (PMID 35163097, 2022). "Therefore, this could be a probable explanation that TRIM37 promote ub-H2A enrichments at the promoters of tumor suppressors, resulting in a reduce of TGF-β1 promoter occupancy and signaling activation." (PMID 34130705, 2021). "Thus, even if there was a clear difference in the predominant tumor types between human patients and Trim37−/− mice our data further strengthens the findings in human MUL patients that deficient function of TRIM37 is associated with increased risk of tumorigenesis." (PMID 27044324, 2016). "TRIM37 overexpression renders RAS-transformed, premalignant breast cells tumorigenic, and inhibition of TRIM37 function reduces tumor growth in xenograft and patient-derived mouse models." (PMID 39614126, 2025). "TRIM37, another member of the TRIM protein family, interacts with epigenetic complexes to regulate gene methylation and ubiquitination, influencing tumor proliferation and differentiation." (PMID 40565099, 2025). "An in vivo experiment was conducted to explore the potential impact of TRIM37 on the growth capacity and sunitinib resistance of RCC cells by establishing a subcutaneous xenotransplant tumor model in nude mice." (PMID 39349442, 2024). "TRIM37, PRC2, and PRC1 are co-bound to tumor suppressive genes, resulting in their transcriptional silencing and oncogenic function." (PMID 33391428, 2021). "It has been found that RPS6KB1, BRIP1, TRIM37, PPM1 D and other tumor-related genes are located in this region." (PMID 34659555, 2021). "Of the eight genes we identified, three genes (RNF7, NPEPPS, and NCCRP1) were down-regulated and the remaining five (BRCA1, TRIM37, RNF25, CDC27, and UBE2H) were up-regulated in tumor tissue compared to normal pancreatic tissue." (PMID 33414811, 2020). "Groups of mice were subcutaneously injected with control, TRIM37-overexpressing, or TRIM37-silenced PANC-1 cells, and the mice were then treated with 5-FU (150 mg/kg) twice per week, beginning when the tumor reached 0.5 cm in diameter." (PMID 33194618, 2020). "Among the eight genes, five genes (BRCA1, TRIM37, RNF25, CDC27, and UBE2H) were significantly upregulated and three genes (RNF7, NPEPPS, and NCCRP1) were significantly down regulated in the tumor tissues." (PMID 33414811, 2020). "To uncover potential molecular factors associated with sunitinib resistance, we performed transcriptome sequencing on tumor tissue with sunitinib resistance and control tissue from a PDX mouse model, revealing significant upregulation of TRIM37 expression in sunitinib-resistant tissue." (PMID 39349442, 2024). "Further RT-qPCR analysis confirmed elevated TRIM37 mRNA expression in RCC tumor tissue compared to adjacent normal tissue." (PMID 39349442, 2024). "Interestingly, ectopic expression of TRIM37 increased proliferation of MCF10AT cells (a premalignant MCF10A cell line, stably expressing HRAS) in vitro and tumor formation in vivo." (PMID 34208621, 2021). "Taken together, abnormal TRIM37 in RCC could ubiquitinate H2A and promote its enrichments at the promoter sites of putative tumor suppressors, thus releasing the occupy of ub-H2A at TGF-β1 promoters and activating its activity." (PMID 34130705, 2021).
tumor (continued). "We classified 124 GC samples into either positive or negative groups according to the intensity of TRIM37 staining among tumor cells, as described in the Materials and methods section." (PMID 33391428, 2021). "In summary, TRIM37 could enhance RCC cells tumorigenic and invasive skills, and function as an oncogenic factor to promote tumor progression via EMT procedure." (PMID 34130705, 2021). "Furthermore, SMARCC2 exhibited diminished expression in tumor tissue, with a negative correlation to TRIM37 levels." (PMID 39349442, 2024). "In terms of tumor metastasis, we observed that the number of tumors formed in the peritoneum of WT and shLacZ control groups was higher than that in the TRIM37 knockdown group (data not shown), demonstrating that TRIM37 plays a positive role in regulating cell metastasis." (PMID 35163097, 2022).